CDKN1A (cyclin dependent kinase inhibitor 1A)
Diseases named in the same sentence as CDKN1A in open-access papers (continued):
Sharing a sentence is not in itself a finding about the gene and the disease.
tumor (continued). "First, we constructed the tumor-specific MRCP for up-regulation of CDKN1A specifically." (PMID 39507755, 2024). "Additionally, CDKN1A upregulation enhanced A549 xenograft tumor radioresistance by inhibiting radiation-induced pyroptosis in vivo." (PMID 38468925, 2024). "The cell cycle inhibitor CDKN1A was originally identified as a tumor suppressor and CDK inhibitor." (PMID 38243250, 2024). "Loss of mitosis in tumor cells is associated with a marked reduction in cyclin-dependent kinase (CDK1) transcription and/or loss of its active form (CDK1-P-Thr 161), which coincides with upregulation of CDKN1A, CDKN1B, and CDKN1C." (PMID 39766809, 2024). "In addition, CDKN1A, as a gene capable of inhibiting cell cycle protein-dependent kinases, is considered to be an important tumor suppressor in the pathogenesis of cancer." (PMID 38517922, 2024). "The expression levels of RanBPM is positively correlated with p21(CDKN1A) in NSCLC tumor samples." (PMID 37676377, 2024). "These upregulated genes (Cdkn1a, Eda2r and Phlda3), are known for their role in cell cycle arrest, apoptosis and tumor suppression, while the most downregulated genes (Hba-a2, Serpina9, and Ms4a1) are associated with hemoglobin synthesis, mitochondrial function and B cell differentiation 34–43." (PMID 36604457, 2023). "To understand the tumor cell-autonomous mechanism underlying the tumor-promoting function of SMIMP and SMC1A, we further investigated the two targets cyclin-dependent kinase inhibitor (CDKN)1A and CDKN2B that have an established role in cell proliferation." (PMID 37932451, 2023). "An additional tumor suppressor mechanism of SOCS1 could be the attenuation of the oncogenic potential of CDKN1A." (PMID 36765862, 2023). "The TCGA data supported our initial patient cohort data with an increase in SRSF3 expression, downregulation of CDKN1A levels and upregulation of miRNAs of the miR‐17‐92 cluster in tumour samples compared with normal tissue, with the largest increase in miR‐17 and miR‐20a levels." (PMID 37306233, 2023). "As a cyclin-dependent kinase (CDK) inhibitor, CDKN1A generally functions as a tumor suppressor." (PMID 36765862, 2023). "CDKN1A is a negative regulator of the Erk/Akt pathway in tumour cells." (PMID 37860579, 2023). "In breast cancer, in which we often observe a downregulation of CDKN1A/p21, this may serve as a predictive marker for elevated stem-like properties in tumours, and thus increased probability of metastasis and recurrence." (PMID 38139316, 2023). "When in the nucleus, CDKN1A functions as a tumour suppressor." (PMID 36765397, 2023). "Pronounced upregulation of CDKN1A in the cell lines that responded synergistically to the drug combination could be as a consequence of its role as a tumour suppressor gene, increasing DNA damage induced apoptosis in these cells." (PMID 35486574, 2022).
tumor (continued). "Moreover, consistent with the in vitro data, western blot analysis revealed that the effects of ESCCAL-1 overexpression on cell cycle regulators (CDK4, CCND1, and CDKN1A) were partially abolished by knockdown of Gal-1 in ESCC tumor tissues." (PMID 35233069, 2022). ",24,41, 42, 43 However, the exact function of CDKN1A in the regulation of cancer cell sensitivity to treatments that exert cytotoxicity by interfering with the stability and synthesis of genetic materials varies among tumor types." (PMID 35505963, 2022). "The first, CDKN1A (p21), is a master senescence marker thus acting as a tumour suppressor." (PMID 35715818, 2022). "Decreased CDKN1A has been found in multiple tumor cells, and several studies have shown that IGFBP3 could effectively inhibit the malignant behaviors of cancer cells." (PMID 35340229, 2022). "On the other hand, somatic driver genomic alterations in CDKN1A are extremely rare, as only 51 out of 10,066 (~0.5%) assessed primary tumor samples appeared to be affected, with the majority detected in bladder urothelial carcinoma (39/51) and hepatocellular carcinoma (7/51) patients." (PMID 35158934, 2022). "FOXD2-AS1 inhibits cyclin-dependent kinase inhibitor 1A (CDKN1A) expression by recruiting enhancer of zeste 2 polycomb repressive complex 2 subunit (EZH2) and is linked to a poor prognosis in patients with OS and promotes tumor progression." (PMID 35659268, 2022). ",29,44, 45, 46 This variation may be explained by the participation of CDKN1A as a master effector in multiple tumor-suppressor pathways that are tightly intertwined, such as cell-cycle arrest, apoptosis, senescence, and DNA repair." (PMID 35505963, 2022). "Besides, knockdown of CDKN1A abolished the anti-tumor effect of inhibition of MSTO2P in HT-29 cells." (PMID 35346226, 2022). "Additionally, Cdkn1a-null mutant mice crossed into an oncogenic Ras mutant background showed increased and accelerated tumor growth compared to WT P21." (PMID 34065345, 2021). "CDKN1A can act as a tumour suppressor or oncogene, depending on the cellular context." (PMID 34804371, 2021). "Moreover, immunohistochemistry assay confirmed that IGF2-AS over-expression in HepG2 cells increased CDKN1A expression, while decreased Ki-67 expression in tumor tissues of xenograft models." (PMID 34516353, 2021). "The CDKN1A gene was initially considered as a potential tumor suppressor." (PMID 34446793, 2021). "In conclusion, IGF2-AS is a tumor-suppressor in HCC, and lower IGF2-AS expression is associated with poor prognosis of HCC patients; IGF2-AS inhibits HCC oncogenesis and development by IGF2-AS/miR-520h/CDKN1A pathway." (PMID 34516353, 2021). "Finally, TISIDB database was used to investigate the role of CDKN1A in tumor-immune system interactions in GBM." (PMID 33621203, 2021).
tumor (continued). "We speculate that since CDKN1A was significantly correlated with various types of tumor-infiltrating lymphocytes, immunoinhibitors, immunostimulators and MHC molecules in GBM, it might exert a more significant effect on immune fingerprinting in GBM." (PMID 33621203, 2021). "In pancreatic cancer, DUXAP8 promotes tumor growth through epigenetic silencing of CDKN1A and KLF2." (PMID 34957112, 2021). "Furthermore, Dcn, Cav1, Cdkn1a, Myc, Qsox1, and Pdgfr-b are known for their role in promoting tumor-cell aggressiveness, EMT and sustaining the proliferation of mesenchymal cells." (PMID 34775465, 2021). "CDKN1A can also exhibit oncogenic activities in some cancers, which may explain the strong correlation of its overexpression with tumor grade, rapid progression, poor prognosis, and drug resistance." (PMID 32079343, 2020). "Here we report in two different cancers sensitive to T cell-mediated rejection, that deletion of the senescence-inducing cell cycle regulators p16Ink4a/p19Arf (Cdkn2a) or p21Cip1 (Cdkn1a) in the tumour cells abrogates both the natural and the ICB-induced cancer immune control." (PMID 32165639, 2020). "Furthermore, the relationship between the oncolytic effect of M1 and the expression of CDKN1A was also analyzed in 44 tumor cell lines, and CDKN1A expression was measured via reversed‐phase protein array (RPPA) in the CCLE database." (PMID 33037696, 2020). "To explore the pathway that miR-3682-3p effected on division and apoptosis, we examined protein level of PHLDA1, Fas (or called TNF receptor superfamily member 6) and cyclin dependent kinase inhibitor 1A (CDKN1A, also known as P21) in vivo by testing transplanted tumor nodules." (PMID 33033502, 2020). "CDKN1A also interacts with GADD45α to mediate tumor suppressor activity." (PMID 31541175, 2019). "Even though no significant risk association for MTC development was identified, perhaps due to the small sample size, extrathyroidal tumor extension was significantly less in patients with the CDKN1A SNP as compared to those with wild type CDKN1A (50% versus 92%, P = .037)." (PMID 31408923, 2019). "Moreover, FAS and CDKN1A were identified as the top downregulated genes in R1 cell-derived tumor xenograft versus parental cell-derived tumor xenograft." (PMID 31013771, 2019). "Thus, its tumor suppression activity is abolished due to disruption in CDKN1A and SMAD3 pathway which is related to cell cycle regulation and aberrant activation of PI3K/AKT pathway." (PMID 30057548, 2018). "To investigate whether CDKN1A acts as a tumour protective factor in TNBC during chemotherapy, we evaluated the effect of knocking down or increasing the expression of CDKN1A on colony formation and apoptosis in MDA-MB-231 cells." (PMID 30497491, 2018).
tumor (continued). "Oral gavage of LP to athymic nude mice bearing A549 NSCLC xenografts significantly down-regulated the expressions of miR-106b and its precursor MIR106B mRNA, and increased CDKN1A mRNA expression in tumor xenografts, correlating to markedly reduced tumor growth." (PMID 29643994, 2018). "Subsequent to that, by qRT-PCR, we found that the CDKN1A expression is lower in CCA tumor tissues in comparison with the neighboring ones through the detection of the expression in a cohort of 17 pairs of CCA tumor tissues in comparison with the nearby tissues using qRT-PCR." (PMID 29970899, 2018). "They identified induction of cyclin-dependent kinase inhibitor 1A (p21) as a common target of urolithins and could link p21 induction with downregulation of onco-miR-224 or upregulation of tumour suppressor miR-215." (PMID 29685968, 2018). "However, we only observed the tumour-promoting effects of the CDKN1A-PTN-PTPRZ1 axis in vitro in the present study, and more evidence related to the therapeutic potential of this axis should be confirmed in vitro and in vivo in the future." (PMID 30497491, 2018). "Microarray analysis revealed the CDKN2A and CDKN1A genes to be significantly repressed in all tumour types vs controls while the CDK2 gene was upregulated in the all tumours vs controls and CDK6 was also upregulated in GH-secreting tumours vs controls (data not shown)." (PMID 28649092, 2017). "Taken together, we could suggest that the regulation of CDKN1A in HCC by several effector genes including PRMT1 can influence tumor growth." (PMID 29383172, 2017). "Moreover, 17 cell cycle markers, including CDK2, CCND1 and CDKN1A, 20 cellular growth and proliferation markers, and other biomarkers for NB or other tumours, were also identified." (PMID 28246384, 2017). "The present analysis showed, for the first time, that the anti-tumor effect of fisetin was mediated mainly through modulation of multiple signaling pathways and via activation of CDKN1A, SEMA3E, GADD45B and GADD45A and down-regulation of TOP2A, KIF20A, CCNB2 and CCNB1 genes." (PMID 28052097, 2017). "In the tumor tissue there was a weak positive correlation of RACGAP1 gene expression with CTNNB1 (r = 0.288, P = 0.033), as well as an inverse association with CDKN1A gene expression (r = −0.357, P = 0.012)." (PMID 26778597, 2016). "To follow up on the possibility that p21 has oncogenic properties in neoplasms of mature B-lymphocytes, and to evaluate the clinical significance, if any, of up-regulation of CDKN1A, we interrogated publicly available gene expression profiles of human non-Hodgkin lymphomas and MM." (PMID 25838973, 2015). "Interestingly, several previous studies have demonstrated an association between a decreased expression of CDKN1A and the recurrence of stage II CRC, along with tumor suppression function in the colon of CDKN1A-deficient mice." (PMID 25799222, 2015). "CDKN1A may exhibit both oncogenic and tumor‐suppressive roles in the progression of cancer." (PMID 41457818, 2026).
tumor (continued). "Notably, CDKN1A (p21), which was found upregulated due to the combination treatment in our study, suggests interference with pathways critical for tumor suppression and may explain the synergetic effect of Onalespib to radiation." (PMID 39949745, 2025). "Consequently, we show that IRF4 controls the expression of tumour suppressor genes known to be silenced by these epigenetic modifications, for instance cyclin-dependent kinase inhibitors CDKN1A and CDKN1B, the PI3-AKT pathway regulator PTEN, and primary cilium components." (PMID 38880659, 2024). "In addition, some miRNAs might be directly involved in regulation of cell cycle progression as suggested by our finding that MIR663A likely inhibits the cell cycle inhibitor CDKN1A across distinct tumor lineages." (PMID 38886809, 2024). "While in normal cells, this would lead to cell cycle arrest, activating mutations in BRAF and NRAS, combined with mutation in tumor suppressors such as PTEN and can result in robust mitogenic signaling and translation of CCND1, which may “override” CDKN1A/p21-mediated checkpoint activation." (PMID 36696495, 2023). "Interestingly, genes encoding CDK inhibitors, such as CDKN1A (p21Cip1), CDKN2A (p16INK4A), CDKN2C (p18INK4C) were downregulated in our CNFPA, which is consistent with a cyclin-mediated oncogenic mechanism, whereby these proteins act as tumor suppressors." (PMID 35260162, 2022). "In addition, CDKN1A expression is related to tumor-infiltrating lymphocytes and immunomodulators." (PMID 33621203, 2021). "Also mice lacking p21, a protein encoded by Cdkn1a gene were healthy but spontaneous tumours developed and G1 checkpoint control was compromised in cells derived from these mice." (PMID 30045727, 2018). "Interestingly, in the tumors of both groups of patients, the autophagy markers P62 and LC3, the anti-apoptotic BCL-2, and the proliferation marker ki-67 were increased compared to non-tumor specimens, while those of the inhibitor of cell proliferation CDKN1A were reduced." (PMID 29371906, 2018). "Thus, we believe that CDKN1A expression may be involved downstream of PRMT1 and that regulation of CDKN1A by PRMT1 plays an important factor for tumor growth and formation in HCC." (PMID 29383172, 2017). "Likewise, in vitro studies on tumor cell lines and clinical outcome results indicated that CDKN1A may be a BL oncogene." (PMID 25838973, 2015). "In addition, PARP-1 and its interaction with the cell cycle control protein p21 (CDKN1A) may also contribute to tumorigenesis and the tumor phenotype." (PMID 24202328, 2013). "In vivo experiments, a xenograft MM mouse model was established using transfected knockout or overexpressing CDKN1A and BCAT2 cell lines, for analyzing the effects of CDKN1A or BCAT2 genes on tumor growth and MM cell autophagy." (PMID 41457818, 2026). "In the RM+ group under 2D conditions, tumour suppressor genes, CDKN1A and NR4A3, were upregulated and tumour-promoting genes, CA9, EFNA1, and SUSD2, were downregulated." (PMID 41381717, 2025).